RN7SL575P (RNA, 7SL, cytoplasmic 575, pseudogene)
Gene: Miscellaneous RNA gene on chromosome 2 (95,003,545 to 95,003,843, reverse strand). Ensembl gene ENSG00000277591.
Homologues: Orthologues: chimpanzee Metazoa_SRP (98% identical). Paralogues in human: RN7SL1 (86% identical), RN7SL2 (85% identical), RN7SL3 (84% identical), RN7SL326P (82% identical), RN7SL44P (82% identical), Metazoa_SRP (81% identical), RN7SL230P (81% identical), RN7SL357P (81% identical), RN7SL45P (81% identical), RN7SL296P (81% identical), RN7SL444P (81% identical), RN7SL627P (81% identical), and 701 more.